HIF1A (hypoxia inducible factor 1 subunit alpha)
Diseases named in the same sentence as HIF1A in open-access papers (continued):
Sharing a sentence is not in itself a finding about the gene and the disease.
cancer (continued). "There have been a few reports on the effect of HIF-1α overexpression on the in vitro biologic properties of cancer cells." (PMID 19919690, 2009). "Two basic expression patterns of HIF-1α in cancer cell lines are known: inducible and constitutive expression." (PMID 19223895, 2009). "In HCC, positive staining of HIF-1α protein was observed mainly in cancer cells, and occasionally in infiltrating lymphocytes as well." (PMID 19948069, 2009). "BRCA1 cancers with positive HIF-1α or cytoplasmic FIH had a significantly shorter relapse-free survival (P=0.007 and P=0.049, respectively)." (PMID 19724277, 2009). "Hypoxia activates signaling through hypoxia-inducible factor (HIF)-1α, which is overexpressed in many cancers, including breast." (PMID 19727403, 2009). "The expression of VEGF in cancer cells is under the control of hypoxia-inducible factor-1α (HIF-1α) which is a transcription factor induced under hypoxia conditions." (PMID 19919679, 2009). "Immunohistochemical analysis of human tumor biopsies has revealed overexpression of HIF-1α in various types of cancer." (PMID 18493321, 2008). "Studies have shown progressively increased HIF-1α expression in breast, skin and cervical cancer development." (PMID 18283323, 2008). "HIF-1α overexpression has been detected via IHC in several human cancers, including those of the brain, bladder, breast, colon, ovary, pancreas, kidney, and prostate." (PMID 18452596, 2008). "Western blotting showed that treatment with ENMD-1198 markedly diminished a hypoxia-induced (1% O2) activation of HIF-1α in cancer cells." (PMID 18651980, 2008). "The frequency of the nuclear expression of HIF-1α in carcinomas was higher than that of borderline tumours, but this difference was not significant (p > 0.05)." (PMID 19014607, 2008). "An enhanced expression of HIF-1α from normal tissue through premalignant lesions to carcinomas has already been observed in prostate, gastric, breast, oral cavity, cervical and endometrial carcinogenesis." (PMID 18983642, 2008). "As such, there is currently interest in the use of HIF-1α inhibition as a cancer therapeutic strategy." (PMID 17179985, 2007). "Increased PI3K and Akt or decreased PTEN activity in cancer cells were also shown to increase HIF-1α." (PMID 19384426, 2007). "Our data suggest that a decrease in HIF-1α levels is indicative of positive responses to EGFR-targeted therapy of cancer cells with either wild-type or tyrosine kinase domain-mutated EGFR." (PMID 17931419, 2007). "Expression of HDACs is often up-regulated under angiogenic stimuli such as hypoxia in cancer cells, and HDACIs can suppress HIF1α expression and its down-stream targets, including VEGF." (PMID 17958916, 2007). "We and others recently found that treatment of responsive cancer cells with cetuximab or gefitinib downregulated the levels of hypoxia-inducible factor-1α (HIF-1α) under both normoxic and hypoxic conditions." (PMID 17931419, 2007). "The gene for LDH-A, whose expression is often increased in cancer cells, has been identified as a c-Myc responsive gene, and is also shown to be induced by hypoxia through the activity of HIF-1α." (PMID 16509995, 2006). "We found that DCPA inhibited HIF-1 expression in a subunit-specific manner in these cancer cell lines induced by serum and growth factors, and decreased HIF-1α expression by affecting its protein stability." (PMID 16884534, 2006). "It has recently been demonstrated that HIF-1α expression is of prognostic value in several types of cancer, including breast cancer." (PMID 16168127, 2005). "In view of its important role in various cancers, we evaluated HIF-1α expression and related proteins such as GLUT 1 and CA IX in SCC of the oral cavity, which has not well been documented." (PMID 16035955, 2005).
cancer (continued). "It therefore seems that HIF-1α and its downstream targets play pivotal roles in the development and progression of cancer." (PMID 16168127, 2005). "Evidence is mounting that HIF-1α and its downstream targets play pivotal roles in the development and progression of many types of human cancers." (PMID 16168127, 2005). "Kaplan-Meier analysis of carcinomas with low HIF 1-α expression (HIF-1α ≤ 5%) showed a significantly poorer disease free (p < 0.01) and overall survival (p < 0.01)." (PMID 16035955, 2005). "In another experiment, HIF-1α+/+ and HIF-1α-/-cells were exposed to long-term hypoxia up to three days, to simulate the chronic conditions that cancer cells go through." (PMID 15341671, 2004). "As seen from the table, differential expression between normal and cancer tissues was much more apparent in Ndrg1 than HIF-1α." (PMID 15341671, 2004). "It has been shown that HIF-1α is a key player in the cancer cells response to low-oxygen tension in a variety of physiologic processes including embryogenesis, angiogenesis, tumorigenesis and metastases." (PMID 12966423, 2003). "In addition to macrophages, cancer-associated fibroblasts (CAFs) secrete glutamine to maintain CCA cell mTORC1 activity and induce the stabilization of HIF-1α in CAFs themselves, forming a positive feedback metabolic loop." (PMID 41513616, 2026). "While our recent work has demonstrated that elevated HP stabilizes HIF-1α expression in cancer cells, here we further investigate whether elevated HP promotes cancer cells to acquire stemness features." (PMID 42224096, 2026). "Therefore, we asserted that the FA‐induced HIF‐1α induction strongly promotes the secretion of specific cytokines from cancer cells, functioning as crucial signaling molecules." (PMID 41160815, 2026). "Primarily, we analyzed the molecular factors, such as HIF1A, EPAS1, and VEGFA gene expression levels, that could influence cancer risk and development." (PMID 39888575, 2026). "In addition, we cocultured cancer cells with ADSCs after silencing CCL2 or HIF‐1α in the cancer cells, thereby inhibiting CCL2 secretion." (PMID 41160815, 2026). "In hypoxic cancer cells, HIF-1α and H19 expression are significantly correlated among lncRNAs." (PMID 41614928, 2026). "After treatment of the CM, HIF‐1α expression levels in the cancer cells were assessed." (PMID 41160815, 2026). "Thus, our data support the existence of a functional FAs/HIF‐1α/CCL2 axis in cancer cells under increased FA supply." (PMID 41160815, 2026). "In addition, targeting the crosstalk between JAK1/2 and HIF1α has been shown to be a promising strategy for cancer treatment." (PMID 41520505, 2026). "The HIF-1α/VEGF axis is identified as a key regulator of angiogenesis in many malignant tumors." (PMID 41438587, 2026). "Similarly, hypoxia-inducible factor 1-alpha (HIF-1α) upregulates the miR-23a/24 cluster, driving a metabolic shift toward glycolysis under hypoxic conditions and thereby accelerating cancer progression." (PMID 40783392, 2025). "Indeed, the genetic diversity of HIF1A and the varying risks of cancer versus CAD protection are intriguing and warrant further investigation." (PMID 41303720, 2025). "Consequently, the development of HIF-1α targeted inhibitors is of great significance for the treatment of cancer." (PMID 40421268, 2025). "Targeting the expression of HIF1A is therefore seen as a potential strategy for cancer therapy." (PMID 40468055, 2025). "Although preliminary and only correlative, these results suggest that HIF1α may be involved in induction of error-prone DNA polymerases in a human cancer." (PMID 39468223, 2025). "Natural compounds such as wogonin, CA, Huaier, and isorhamnetin have demonstrated efficacy in overcoming hypoxia‐induced drug resistance or suppressing EMT and carcinogenesis by affecting PI3K/AKT/HIF‐1α, consequently reducing glycolysis, angiogenesis, and metastatic potential in cancers." (PMID 40740483, 2025).
cancer (continued). "Additionally, studies have also reported that hypoxia-related lncRNAs such as PVT1, DANCR, and HIFCAR facilitate the stabilization and transcriptional network of HIF-1α to facilitate cancer progression." (PMID 40004471, 2025). "Based on our in vitro data illustrating 2-ANPC’s potency in decreasing HIF-1α in cancer lines, we examined whether the antitumor activity of this amino-pyrrole derivative was due to its ability to decrease HIF-1α expression in vivo." (PMID 41514626, 2025). "No other study has investigated the association between HIF1A rs11549465 and response to chemotherapy and survival in MM, and there were only a few studies in other cancers." (PMID 40959922, 2025). "Cancer cells transcribe the HIF-1α gene to adapt to the low-oxygen conditions of hypoxia." (PMID 40430040, 2025). "Given the critical role of HIF1α in TFE3‐RCC development, inhibiting HIF1α may be an effective therapeutic strategy for treating this cancer subtype." (PMID 39807625, 2025). "Therefore, blockade of the HIF‐1α/CEPT1/PC signalling axis has emerged as a promising therapeutic strategy for preventing cancer cell metastasis in GC." (PMID 40954549, 2025). "Furthermore, P4HA1 can promote resistance to chemotherapy by regulating the HIF-1α-dependent cancer cell stemness." (PMID 40379610, 2025). "In pathological conditions, excessive HIF-1α activity promotes cancer progression and fibrosis." (PMID 40650173, 2025). "These macrophages promote ascite formation and cancer metastasis through the HIF1α/SPP1 pathway." (PMID 39921309, 2025). "Hypoxic within the cancer niches induces cancer cells to enhance glycolysis, inhibit aerobic respiration, and stimulate neovascularization to improve oxygen supply through the activation of HIF-1α and other signaling pathways." (PMID 39744225, 2025). "This research showed that AQP1 and HIF-1α could be selected as potential targets for cancer therapy and cellular senescence." (PMID 40011266, 2025). "Moreover, HIF1-α regulates angiogenesis, which is vital for cancer cell survival and growth in low-oxygen environments." (PMID 39940704, 2025). "HIF1α plays a critical role in stimulating angiogenesis via upregulating VEGF in different cancers." (PMID 40045186, 2025). "In cancer, hypoxia induces an inflammatory fibroblast phenotype in a HIF-1α–dependent manner." (PMID 40111415, 2025). "Similarly, circPIP5K1A is upregulated in NSCLC cells and modulates cancer cell proliferation and metastasis by binding to miR-600 and activating HIF-1α." (PMID 40004471, 2025). "This resistance is associated with upregulation of HIF-1α, a transcription factor that enhances glycolytic metabolism and is further regulated by the PI3K/AKT pathway—one of the key dysregulated signaling pathways in cancer." (PMID 40149916, 2025). "The HIF-1α subunit is the most prominent, playing a crucial role in cancer development." (PMID 39757165, 2025). "Additionally, combining HIF-1α inhibitors with adoptive T cell therapies or cancer vaccines can enhance immune cell trafficking and activation within the TME." (PMID 39981236, 2025). "Given that PC can modulate cancer cell survival and metastasis, we hypothesised that HIF‐1α enhances the metastatic and antiapoptotic capacities of CM GC cells via the PC content." (PMID 40954549, 2025). "Additionally, the HIF-1α-dependent release of VEGF contributes to increased invasiveness during cancer progression and metastasis." (PMID 39812050, 2025). "Under hypoxic conditions, HIF-1α is stabilized by forming a dimer with the β subunit and is involved in various processes like angiogenesis, metabolic reprogramming, and cell proliferation, which can potentially promote the development of cancer." (PMID 39996906, 2025). "Another role in cellular complexion and cancer resistance of HIF-1α." (PMID 40011266, 2025).
cancer (continued). "Such discrepancies between our results and those of related studies may be due to the complex and diverse mechanisms through which HIF-1A promotes chemo- and radio-resistance in cancer cells." (PMID 40959922, 2025). "This might also interfere with HIF-1α’s stability and promote its degradation, thereby leading to a significant decrease in HIF-1α expression in 2-ANPC-treated cancer cells." (PMID 41514626, 2025). "Moreover, recent research has shown that IL-6 secreted by adipocytes drives STAT3 signaling to induce HIF1α in cancer cells, with HIF1α known to regulate ANGPTL4 expression." (PMID 40616161, 2025). "However, HIF-1α occurs at statistically significantly higher levels in the plasma of patients with a family history of cancer." (PMID 40429943, 2025). "While HIF-1α targeting could be effective in treating some cancers, it is important to consider the potential complications for diabetic patients." (PMID 39996906, 2025). "This may be due to the dominant expression of HIF2α in ccRCC or the cancer-specific functional variation between HIF1α and HIF2α in ccRCC." (PMID 40775208, 2025). "Notably, the epidermal growth factor receptor (EGFR) is a prime example, where a strong correlation exists between EGFR-driven cancers and increased HIF-1α levels across various cancer types, even under normoxic conditions." (PMID 39470609, 2025). "Single inhibitors of glycolysis often fail due to the metabolic flexibility of cancer cells; therefore, future therapies should target HIF1α (e.g., via WWOX), which may more effectively inhibit aberrant glycolysis." (PMID 41007296, 2025). "However, many inhibitors of HIF-1α have passed phase II clinical trials and achieved high remission rates in cancer patients with high HIF-1α expression." (PMID 40563539, 2025). "This is a non-cancer cell-mediated mechanism by which HIF-1α levels are regulated in cancer cells." (PMID 40746883, 2025). "Furthermore, plerixafor decreases HIF1α, a downstream key force in cancer adaptation to hypoxic conditions, and decreases cancer cell survival." (PMID 41383468, 2025). "HIF-1α overexpression is observed in many cancer types and may play a crucial role in the continued growth, differentiation, and metastasis of solid tumors." (PMID 41305000, 2025). "HIF‐1α is a key TF involved in cancer progression and targeted therapy." (PMID 40608530, 2025). "HIF-1α is a key regulator of cancer cell metabolism under hypoxic conditions." (PMID 39859448, 2025). "HIF-1α is an attractive therapeutic target since this subunit stands as a master regulator of the cellular hypoxic response, orchestrating a complex adaptive mechanism in cancer biology." (PMID 40507913, 2025). "In addition to its established roles in metabolism and signalling, our analyses identified through our analyses that the WWOX/HIF1A expression ratio emerges as a pivotal determinant of genomic integrity and DNA repair fidelity across multiple cancer types." (PMID 41007296, 2025). "WWOX and HIF1α proteins are involved in cancer progression; their functions are closely related." (PMID 41007296, 2025). "In the osteoblasts_Gapd2 subpopulation, pathways such as proteoglycans in cancer (Col1a1, Col1a2, Hcls1, Hif1a, Stat3, Vav1), IL-17 signaling (Mmp13, Mmp3, S100a9, Ccl7, Cebpb), and ECM–receptor interaction (Col11a2, Col1a1, Ibsp, and Tnn) were activated (p < 0.05)." (PMID 41459160, 2025). "Given that ASH1L promotes bone metastasis and induces HIF-1α transcriptome, we hypothesize that, in addition to reprogramming pro-metastatic genes in invading cancer cells, ASH1L has a cell-extrinsic role of remodeling the bone niche." (PMID 40394007, 2025). "Additionally, hypoxia-inducible factor 1-alpha (HIF1A) promotes cancer progression through mechanisms such as angiogenesis, metastasis, and alterations in cell proliferation and metabolism." (PMID 40141751, 2025).
cancer (continued). "However, it also helps stabilize the hypoxia-inducible factor-1α (HIF-1α) protein that responds to low oxygen levels, a condition often found in various cancers." (PMID 40694594, 2025). "Furthermore, physical interactions between HIF-1α and Smad proteins have been reported in other cancer types." (PMID 40406267, 2025). "For instance, quercetin enhances apoptosis and autophagy in cancer by reducing β-catenin expression, stabilizing hypoxia-inducible factor 1 alpha (HIF-1α), inhibiting Akt, mTOR, and extracellular signal-regulated kinase (ERK) activation, and activating caspase-3." (PMID 40219344, 2025). "ASH1L rewires histone methylations and cooperates with HIF-1α to induce pro-metastatic transcriptome in invading cancer cells, resulting in monocyte differentiation into lipid-associated macrophage (LA-TAM) and enhancing their pro-tumoral phenotype in the metastatic bone niche." (PMID 40394007, 2025). "Similarly, the constitutive expression of HIF-1α is induced by intermittent tissue hypoxia as cancer cells approach their thresholds for oxygen diffusion mediated by blood vessels." (PMID 40441532, 2025). "However, the impact of PP extract on cancer cell metabolism under hypoxic conditions—particularly its influence on HIF-1α signaling and glycolysis—remains unexplored." (PMID 40647184, 2025). "In addition to its role in cancer, HIF-1α also plays essential roles in physiological hypoxic responses." (PMID 40760493, 2025). "HIF-1α plays a critical role in various types of cancer, including NSCLC." (PMID 40860815, 2025). "The hypoxic obese PRAT microenvironment may promote cancer progression by hypoxia-induced factor 1α (HIF-1α) signaling activation and upregulation of CCL2, TNF-α, IL-10, IL-8, and IL-6 pro-inflammatory cytokine expression via NF-κB-pathway stimulation." (PMID 40227577, 2025). "In conclusion, the WWOX/HIF1A expression ratio might be considered as a potential biomarker determining the prognosis of cancer patients." (PMID 41007296, 2025). "KEGG pathway analysis further highlighted the activation of pathways associated with cellular senescence, Wnt signaling, pluripotency regulation, focal adhesion, and autophagy, confirming that both HIF1α and HIF2α regulate cell senescence and drive the formation of cancer stem-like cells." (PMID 40253386, 2025). "The activation of HIF1α is considered a key factor in EMT induction in cancer cells." (PMID 39942749, 2025). "A statistically significant result was obtained only for HIF-1α levels depending on whether there was cancer in the family history." (PMID 40429943, 2025). "Additionally, it is noteworthy that PPARα has been reported to suppress HIF1α protein expression in cancer cells, despite HIF1α being critical for the regulation of glycolysis in living cells." (PMID 40616161, 2025). "By targeting HIF-1α and PI3K/AKT, certain flavonoids can interfere with the metabolic reprogramming that underlies drug resistance, thereby reducing the survival advantage of cancer cells." (PMID 40149916, 2025). "Targeting hypoxia and immunosuppression through HIF-1α inhibitors and immune checkpoint inhibitors may enhance ferroptosis induction by destabilizing protective features of the cancer microenvironment." (PMID 40821110, 2025). "Importantly, we found costaining of PPARδ and the hypoxia marker HIF1α in specific groups of cancer cells heavily surrounded by stromal cells, further reinforcing a direct link between both pathways." (PMID 40607925, 2025). "Chemicals targeting the HIF-1α for cancer therapy (↑ increase, ↓ decrease)." (PMID 41585262, 2025). "HIF-1α could thus have a critical role in cancer resistance to chemotherapeutics and aggressiveness and in understanding its regulation in normoxic environments." (PMID 40032892, 2025).